APOA1 (apolipoprotein A1)
Diseases named in the same sentence as APOA1 in open-access papers (continued):
Sharing a sentence is not in itself a finding about the gene and the disease.
diabetes (continued). "In a meta-analysis of patients with or without diabetes treated with statins, an increase in HDL-C levels after treatment had no significant cardiovascular benefit, whereas an increase in ApoA1 resulted in a substantial reduction in cardiovascular events." (PMID 38914982, 2024). "Through LASSO and logistic regression, our study revealed that gender, diabetes duration, non-HDL-C, APOA1, Lp(a), HCY, AIP, NCV, and carotid plaque were the key predictors of CHD in patients with T2DM." (PMID 36440044, 2022). "Comparing the immunological makers in both groups, subjects in the DFU group showed a lower ApoA1 and IL-10 but higher TNF-α when compared to patients with diabetes without foot ulcers (Group- I)." (PMID 35836916, 2022). "Multivariate logistic regression revealed that gender, diabetes duration, non-HDL-C, APOA1, Lp(a), HCY, AIP, NCV, and carotid plaque were the key predictors of CHD in patients with T2DM." (PMID 36440044, 2022). "The differences in age, sex, hypertension, diabetes, smoking, drinking, BMI, WBC, TC, LDL-C, HDL-C, and ApoA1 were not statistically significant in the three groups, but the differences in TG and CRP were statistically significant (P < 0.001)." (PMID 34235188, 2021). "After adjusting sex, age, BMI, smoking, drinking, history of CHD, hypertension, and diabetes or HDL-C, apoA1, TC, TG, and LDL-C, CCL2 was still negatively correlated with HDL2." (PMID 27458015, 2016). "Recent observational studies showed that the ApoB/ApoA1 ratio can predict the progression of non-major coronary artery lesions and the occurrence of MACE in patients with diabetes complicated with acute coronary syndrome after percutaneous coronary intervention." (PMID 38310324, 2024). "Low HDL cholesterol concentrations among people with diabetes may indicate a specific reduction in large HDL particles (as well as a possible increase in small HDL particles), which may not necessarily significantly reduce apoA1 levels." (PMID 21159217, 2011).
dyslipidemia (221 papers, 2010 to 2026). "An increase in the apolipoprotein B (APOB) to APOA1 ratio is associated with the worsening of metabolic syndrome (MetS) components in PCOS, including IR, elevated androgen levels, and increased liver enzyme levels." (PMID 40083347, 2025). "Given the significant role metabolic syndrome plays in cardiovascular risk and most participants in our study demonstrate the metabolic syndrome, the use of ApoB/ApoA1 is most germane and adds more evidence for its use in the clinical setting." (PMID 35295919, 2022). "Our results indicate that dyslipidemia, in particular low levels of ApoA1, is associated with an increased potential of all monocyte subsets to extravasate, and to do so using a wider repertoire of recruitment markers than currently appreciated." (PMID 33717107, 2021). "Authors found that higher FGF23 levels were associated with obesity, dyslipidemia (lower HDL cholesterol and apolipoprotein A1, higher triglyceride), and increased risk of presenting metabolic syndrome." (PMID 34208131, 2021). "In recent years, high levels of ApoB and low levels of ApoA1 have been found to be associated with the higher risk of cardiovascular disease, metabolic syndrome, ischemic stroke, and Alzheimer's disease." (PMID 34961824, 2021). "Multiple epidemiological studies have shown that low levels of HDL and APOA1 are considered an independent and traditional risk factor of several diseases including coronary artery diseases, metabolic syndromes, dyslipidemias, and multiple cancer types." (PMID 32120838, 2020). "Logistic regression analysis was performed to explore the relationship of APOA1/C3/A4/A5-ZPR1-BUD13 gene cluster gene polymorphisms with dyslipidemia." (PMID 30631647, 2019). "In previous reports, the APOA1 rs670 polymorphism was found to be correlated with dyslipidemia and HDL-C levels." (PMID 29758034, 2018). "With its risk conferring nature towards dyslipidemia, rs632153 emerges as a prominent intronic variant of APOA1 gene from our analysis." (PMID 28610615, 2017). "Further, of the two upstream variants from APOC3 (rs2854116) and APOA1 (rs632153) that were associated with the disease, only APOA1 is risk conferring towards dyslipidemia." (PMID 28610615, 2017). "Recently, several studies have reported that the apoB/apoA1 ratio is associated with metabolic syndrome in different ethnical groups." (PMID 24886173, 2014). "The rs964184 variant in APOA1 has been associated with blood lipid levels, polygenic dyslipidemia, metabolic syndrome, coronary heart disease, and myocardial infarction." (PMID 24922540, 2014). "Visceral adiposity is known to be associated with an elevated ApoB/ApoA1 ratio with is considered to be a risk factor for metabolic syndrome." (PMID 23442518, 2013). "SNPs on the APOA1/C3/A5 gene cluster, which is involved in lipid metabolism, are highly associated with dyslipidemia, metabolic syndrome, insulin resistance and responsiveness to relative treatments." (PMID 23829168, 2013). "Variants in the APOA5-ZNF259 region (including rs3741298) were associated with HDL-C and ApoA-1 response to therapy with statins and fenofibric acid in patients with dyslipidemia." (PMID 23251661, 2012). "The analysis of the PCSF subnetwork showed that proteins associated with the EGFR and APOA1 pathways were generally decreased in serum samples collected from subjects with metabolic syndrome and MASLD at the end of 4-week DDDF compared with the serum collected before 4-week DDDF." (PMID 40551123, 2025). "Additionally, a retrospective study indicated that NHHR offers superior diagnostic value for metabolic syndrome compared to commonly used metrics like apolipoprotein B/apolipoprotein A1 ratios." (PMID 40084133, 2025).
dyslipidemia (continued). "The analysis of the PCSF subnetwork showed that proteins associated with the EGFR and APOA1 pathways were generally decreased in serum samples taken from subjects with metabolic syndrome and MASLD at the end of 4-week DDDF compared with the serum collected before 4-week DDDF." (PMID 40551123, 2025). "Although several studies have investigated risk factors for dyslipidemia, such as diet, obesity, and lifestyle, few studies have extensively investigated the relationship between insomnia and abnormal apolipoprotein levels (including ApoA-1, ApoB and LPA)." (PMID 38087303, 2023). "Many studies have found an association of ApoA1 and ApoB in obesity and metabolic syndrome." (PMID 35558744, 2022). "Children with OB are at almost two times the risk of high ApoB (OR = 1.97), and around two and a half times the risk for high TG (OR = 2.45), low ApoA1 (OR = 2.57), and dyslipidemia (OR = 2.54), and more than four and half times the risk for low HDL (OR = 4.75)." (PMID 34886385, 2021). "SNPs in the APOA1/C3/A4/A5-ZPR1-BUD13 gene cluster were associated with dyslipidemia." (PMID 30631647, 2019). "Furthermore, the association of APOA1 rs5072 in this gene cluster with dyslipidemia differed between genders; thus, additional studies are needed to confirm this conclusion, and the mechanisms underlying these results warrant further exploration." (PMID 30631647, 2019). "Based on previous observations, we hypothesized that dyslipidemia is jointly caused by the APOA1, ABCA1, and LCAT genes and their interactions with environmental factors." (PMID 29758034, 2018). "Associations between APOA1/C3/A4/A5 Gene cluster haplotypes and risk of metabolic syndrome." (PMID 26824674, 2016). "A study in four Finnish cohorts encompassing 11,616 individuals identified a SNP, rs964184, near the APOA1/C3/A4/A5 gene cluster on chromosome 11 as being associated with metabolic syndrome confirming a strong lipid gene component to the genetics of the metabolic syndrome." (PMID 27312935, 2016). "Taken together, these data provide more insights about the variants at the APOA1/C3/A4/A5-ZPR1-BUD13 gene cluster as a relevant risk factor for dyslipidemias such as HTG and low HDL-C, and highlight the notion that these could be biomarkers for susceptibility to these traits." (PMID 35669185, 2022). "Changes in the levels of both HDL-C and triglycerides found to exert stronger effects among women may partially explain this observation In the INTERHEART study, dyslipidemia, defined as the ratio of (ApoB100)/(ApoA1), possessed the highest population-attributed risk in both sexes." (PMID 32225033, 2020). "Therefore, to explore gene-gene and gene-environment interactions underlying dyslipidemia, we investigated five (rs670, rs1800976, rs4149313, rs2292318, rs1109166) single nucleotide polymorphisms (SNPs) located in APOA1, ABCA1, and LCAT based on a model RCT pathway." (PMID 29758034, 2018). "Thus we reasoned that dyslipidemia-associated nucleotide polymorphisms (SNPs) on the APOA1/C3/A5 gene cluster may predict breast cancer risk and tumor progression." (PMID 23829168, 2013). "One particularly intriguing aspect is the observed downregulation of APOA1 in serum collected from subjects with metabolic syndrome and MASLD." (PMID 40551123, 2025). "This highlights the fact that hypoalphalipoproteinemia is the main dyslipidemia detected in the Mexican population, partly as a consequence of the high prevalence of polymorphisms in the CETP, APOA1, and ABCA1 genes." (PMID 37892400, 2023). "GWASs have also identified other common SNPs contributing to dyslipidemia located in or near the APOA1/C3/A4/A5 haplotype." (PMID 37510094, 2023). "Our data imply that more research into ApoA1 is needed to understand the links between dyslipidemia and CVD and vitamin D and CVD." (PMID 36140721, 2022).
dyslipidemia (continued). "With the exception of the novel loci identified in our investigation, subsequent GO and KEGG pathway analyses of the remaining significant loci related to ApoA1 and ApoB/ApoA1 showed a dyslipidemia-related function." (PMID 36140721, 2022). "Existing studies established that high levels of oxidative stress and Hcy were closely associated with dyslipidemia due to their ability to affect cholesterol and lipoproteins, including HDL, LDL and ApoA1." (PMID 35624693, 2022). "Upon admission to surgery, the subjects in the present study had low levels of HDL (1.1 mmol/L) and ApoA1 (1.1 g/L), which is typical for obese dyslipidemia." (PMID 35745111, 2022). "The increased expression of apolipoprotein, particularly HDL-c-related ApoA-1 and ApoA-II, is also beneficial to improved dyslipidemia with its cholesterol-lowering function." (PMID 36234935, 2022). "ApoA-1 is sensitive to the doxorubicin-induced oxidative damage, leading to dyslipidemia and increased circulating TNF-α." (PMID 34055643, 2021). "In contrast, HDL-C and ApoA1 levels and ApoA1/ApoB ratio were significantly lower in the dyslipidemia group than in the normal group (P < 0.001)." (PMID 33612478, 2021). "Both CM-Mexico City and NM-Urban showed a higher risk of high TG, high TC, and dyslipidemia, while CM-Puebla showed a higher risk of low HDL and NM-Yaquis showed a higher risk of low ApoA1 compared to the other four ethnicities, respectively." (PMID 34886385, 2021). "Similar to other biochemicals in the circulation, ApoA-1 is sensitive to the doxorubicin-induced oxidative damage, leading to dyslipidemia and increased circulating TNF-α in the doxorubicin- injection animals, resulting in cognitive impairment." (PMID 34055643, 2021). "APOA1 is a primary lipoprotein associated with serum HDL concentrations in T2DM, and rs5072 of APOA1 is related to dyslipidemia in a gender-specific manner, as shown in the present study." (PMID 33803960, 2021). "In conclusion, we analyzed and assessed the association between APOA1/C3/A4/A5-ZPR1-BUD13 gene cluster gene polymorphisms and dyslipidemia between sexes." (PMID 30631647, 2019). "Association between APOA1/C3/A4/A5-ZPR1-BUD13 gene cluster haplotypes and the risk for dyslipidemia." (PMID 30631647, 2019). "The study applied a large sample design to study the association between the APOA1/C3/A4/A5-ZPR1-BUD13 gene cluster gene polymorphisms and dyslipidemia." (PMID 30631647, 2019). "In our study, we obtained the novel finding of sex-specific differences between the APOA1/C3/A4/A5-ZPR1-BUD13 gene cluster gene polymorphisms and dyslipidemia." (PMID 30631647, 2019). "In the current study, we explored associations of APOA1, ABCA1, and LCAT genes with dyslipidemia and focused on gene polymorphisms involved in the RCT system." (PMID 29758034, 2018). "Our findings suggested that the interaction among APOA1, ABCA1, LCAT conferred the genetic susceptibility to dyslipidemia in Xinjiang Rural Area." (PMID 29758034, 2018). "The association found between vitamin D and dyslipidemia (i.e. HDL-cholesterol and apolipoprotein A1) had previously been described." (PMID 30513089, 2018). "In conclusion, both RYGB and SG induce a significant increase in HDL and ApoA1, and a decrease in LDL, oxLDL and ApoB, in women with severe obesity and a high cardiovascular risk defined by the presence of the metabolic syndrome." (PMID 29925393, 2018). "The aim of this study was to examine the interaction of dietary food groups and genetic variants of APOA1/APOC3, relative to Metabolic Syndrome (MetS) risk in adults." (PMID 28496949, 2017). "The haplotype of rs2483058C-rs2580520G was associated with an increased risk of dyslipidemia (OR: 1.44, 95% CI: 1.17–1.78, P < 0.001), it showed consistent association with serum TC, HDL-C, ApoA1 and the ratio of ApoA1 to ApoB." (PMID 28912560, 2017).
dyslipidemia (continued). "In the present study, apigenin markedly decreased plasma total-cholesterol levels, as well as plasma apoB levels and the apoB/apoA1 ratio, indicating its protective role against atherogenic dyslipidemia in HFD-induced obese mice." (PMID 27213439, 2016). "They recently observed that low circulating Lp(a) associated with high ApoA1/HDL-C ratio were predicting factors for hypertriglyceridemic waist phenotype, which is considered as the core of the metabolic syndrome in impacting coronary heart disease risk." (PMID 25849372, 2015). "APOA1 rs670 is associated with altered HDL-C levels, and increased risks of coronary artery disease and metabolic syndrome." (PMID 23829168, 2013). "Also, rs180365 (LINC02702‐BUD13), rs964184 (ZPR1), rs662799 (ZPR1), rs10750097 (novel APOA5), rs6589574 (APOA1), rs562179 (novel SIK3), associated with lipid‐related traits and/or metabolic syndrome, showed evidence of interaction with TSS of APOA1." (PMID 40665476, 2025). "Notably, certain metabolites such as glycoprotein acetyls, ApoB/ApoA1 ratio, and lactate emerge as promising biomarkers for insulin resistance and metabolic syndrome, suggesting their potential utility in clinical settings." (PMID 40507103, 2025). "Similarly, variants in the 11223.3 chromosomal region involving APOA1, APOA4, APOA5, and APOC loci were reported to be strongly influencing the lipid levels and dyslipidemia in studies from northern and southern India." (PMID 38348409, 2023). "Contrary to previous findings regarding APOA1 expression in lung cancer, a recent study found that APOA1 levels were increased in patients with idiopathic pulmonary fibrosis-related lung cancer, resulting in dyslipidemia." (PMID 38067270, 2023). "Furthermore, among patients with the metabolic syndrome smoking reduced plasma ApoA1 and a positive association with the HDL-c/ApoA1 ratio indicating a shift towards smaller HDL particle size." (PMID 36050733, 2022). "Several studies have investigated the impact of ApoA1 genetic polymorphisms on dyslipidemia and CVD risks, but the considerable effect of ApoA1 polymorphisms among different ethnic populations and their association with the risk of arterial stiffness in older people was limited." (PMID 35873099, 2022). "In addition, the ApoB/ApoA1 ratio is now widely used to predict the occurrence of CVDs and metabolic syndrome because it is a composite index that comprehensively reflects the lipid metabolism balance." (PMID 36140721, 2022). "Furthermore, in people with hypertriglyceridemia, type II diabetes, or metabolic syndrome, the protective ApoA-I values are also low, creating a high and “risky” ApoB/ApoA-1 ratio value." (PMID 34952923, 2021). "The ApoB/ApoA1 ratio is a promising diagnostic tool for metabolic syndrome (MS) in different populations, though its use is not established in Kazakhstan." (PMID 32717783, 2020). "Therefore, this study explored the relationship between the APOA1/C3/A4/A5-ZPR1-BUD13 gene cluster gene polymorphisms and dyslipidemia in the total sample population and stratified by genders in a northeast Chinese population." (PMID 30631647, 2019). "The levels of weight, percent of smoking and drinking, serum glucose, serum TC, triglyceride (TG) and LDL-C were higher, as well as the levels of serum high-density lipoprotein cholesterol (HDL-C) and the ratio of ApoA1 to ApoB were lower in dyslipidemia than in normal groups (P < 0.05–0.001)." (PMID 29670124, 2018). "However, it has also been reported that TG-rich, apoA-1-poor small dense HDL has an anti-atherogenic effect in patients with metabolic syndrome." (PMID 29159568, 2018). "Thus, dyslipidemia is influenced by APOA1, ABCA1, LCAT, environmental factors, and their interactions." (PMID 29758034, 2018). "Furthermore, other studies have reported a link between vitamin D status and dyslipidemias and showed that low 25(OH)D concentrations were associated with increased TG and decreased HDL-C or apolipoprotein A1 levels." (PMID 30166978, 2018).